CCL18 (C-C motif chemokine ligand 18)
Description:
Chemotactic factor that attracts lymphocytes but not monocytes or granulocytes. May be involved in B-cell migration into B-cell follicles in lymph nodes. Attracts naive T-lymphocytes toward dendritic cells and activated macrophages in lymph nodes, has chemotactic activity for naive T-cells, CD4+ and CD8+ T-cells and thus may play a role in both humoral and cell-mediated immunity responses.
Synonyms: AMAC-1; DC-CK1; MIP-4; AMAC1; DCCK1; PARC; SCYA18; CKb7
Tractability: Antibody: UniProt places it where antibodies can reach, with medium confidence; UniProt predicts a signal peptide or a membrane-spanning region; its Gene Ontology location is reachable by antibodies, with medium confidence.
Gene: Protein-coding gene on chromosome 17 (36,064,272 to 36,072,032, forward strand). Ensembl gene ENSG00000275385.
Subcellular location: Secreted
Gene Ontology:
Molecular function: protein binding; CCR chemokine receptor binding; chemokine activity
Biological process: antimicrobial humoral immune response mediated by antimicrobial peptide; cell chemotaxis; cell communication; cell-cell signaling; chemokine-mediated signaling pathway; chemotaxis; immune response; inflammatory response; positive regulation of cell migration; signal transduction
Cellular component: extracellular region
Genetic constraint (gnomAD): Loss-of-function variants: 6 observed, 6.4 expected, observed/expected ratio (o/e) 0.94, 90% interval 0.51 to 1.72. That is too few expected variants to judge how well the gene tolerates losing a copy. Missense variants: 73 observed, 92.69 expected, observed/expected ratio (o/e) 0.79, 90% interval 0.65 to 0.96. Synonymous variants: 31 observed, 37.6 expected, observed/expected ratio (o/e) 0.82, 90% interval 0.62 to 1.11.
Homologues: Orthologues: chimpanzee CCL18 (98% identical), macaque CCL18 (91% identical), rat Ccl3 (58% identical), mouse Ccl3 (57% identical), dog CCL3 (56% identical), pig CCL3L1 (56% identical), zebrafish ccl35.1 (33% identical), zebrafish ccl35.2 (33% identical). Paralogues in human: CCL3 (63% identical), CCL3L3 (62% identical), CCL14 (43% identical), CCL23 (43% identical), CCL4 (43% identical), CCL15 (42% identical), CCL4L2 (42% identical), CCL26 (38% identical), CCL5 (38% identical), CCL11 (36% identical), CCL16 (36% identical), CCL7 (36% identical), and 14 more.
Diseases named in the same sentence as CCL18 in open-access papers:
CCL18 is named in the same sentence as 228 diseases in open-access papers, as found by Europe PMC text mining. Sharing a sentence is not in itself a finding about the gene and the disease. The quoted sentences say what the papers report.
breast carcinoma (109 papers, 2013 to 2025). "On the other hand, DEGs such as CCL18 is associated with angiogenesis in breast cancer, demonstrating the potential of DYN to represent the dynamics in DCE-MRI." (PMID 38745321, 2024). "In this study, we found that CCL18 expression was positively correlated with the density of CD10+GPR77+ CAFs in breast cancer and associated with a poor response to chemotherapy." (PMID 36418470, 2023). "TAMs are a primary source of CCL18, a chemokine associated with breast cancer progression and poor prognosis." (PMID 35202089, 2022). "A previous study revealed that Treg cells in human breast cancer are mainly derived from naïve CD4 + T cells recruited by tumor-associated macrophage-derived CCL18." (PMID 36221095, 2022). "Recently, it was demonstrated that CCL18 released from tumor-associated macrophages can promote angiogenesis in breast cancer independently of VEGF-R signaling." (PMID 35159163, 2022). "CCL18 was previously reported to be released from tumor-associated Mφ in breast cancer, promoting angiogenesis and tumor progression, and we deepened the understanding of this factor in lung cancer." (PMID 36008393, 2022). "High levels of CCL18 can be linked to cancer progression in colon cancer, breast cancer, and prostate cancer, where CCL18 not only activates recruitment of Tregs but also stimulates cancer cell migration and angiogenesis." (PMID 34937192, 2021). "In that regard, tumor cells recruit and activate M2-like macrophages, which then produce M2-related cytokines, such as CCL18, which causes breast cancer cells to elongate, lose contact inhibition, and increase vimentin expression." (PMID 33968034, 2021). "In breast cancer patients, tumor-associated macrophages (TAMs) with M2 phenotype abundantly produce CCL18, and its expression in blood or cancer stroma is associated with metastasis and reduced patient survival." (PMID 30979916, 2019). "Chemokine (C-C motif) ligand 18 (CCL18) is derived from tumor-associated macrophages and has shown an ability to facilitate breast cancer metastasis." (PMID 29738483, 2018). "CCL18 from tumor-associated macrophage facilitates cancer metastasis of ovarian cancer, breast cancer and pancreatic ductal adenocarcinoma." (PMID 30723697, 2018). "CCL18 expression by tumor-associated macrophages was recently shown to be essential for cancer metastasis in a humanized mouse model of breast cancer." (PMID 29100308, 2017). "In breast cancer samples, the expression of GM-CSF in high levels is associated with the increase in CCL18(+) macrophages and the realization of EMT by cancer cells, which both translate into an increase of metastasis and a reduction of patient survival." (PMID 28567162, 2017). "CDDO-Me also decreased mRNA expression of CCL18, which has been implicated in promoting breast cancer metastasis and is highly expressed by human TAMs and M2-activated macrophages." (PMID 26918785, 2016). "Our previous work has indicated that CCL18 secreted by tumor-associated macrophages (TAMs) promotes breast cancer metastasis, which is associated with poor patient prognosis." (PMID 26244871, 2015). "We demonstrated that CCL18+ TAM infiltration positively associated with MVD in breast cancer samples, which was correlated with tumor metastasis and poor prognosis." (PMID 26416449, 2015). "In addition, there was a reverse causal association between CCL1 (OR = 0.94) and CCL18 (OR = 0.94) and breast cancer." (PMID 38075694, 2023). "Pseudobulk analysis on the myeloid cell fraction (monocytes, macrophages and DCs, excluding granulocytes) showed that several cytokine-encoding mRNAs were overexpressed in IE1, most notably CCL18, which has previously been associated with breast cancer metastasis." (PMID 36609566, 2023). "In addition to angiogenesis, CCL18 production from TAMs has also been associated with tumor invasiveness and metastasis in breast cancer." (PMID 33968034, 2021).
breast carcinoma (continued). "In breast cancer cells, CCL18 also activates the p300/CBP-associated factor (PCAF)." (PMID 33114763, 2020). "Finally, the high expression of CSF2 in breast cancer is associated with more CC chemokine ligand 18 (CCL18)+ macrophage infiltration, epithelial-mesenchymal transition (EMT), enhanced metastasis, and reduced patient survival." (PMID 33224886, 2020). "Song's team determined that serum CCL18 was obviously elevated in patients with breast carcinoma, and high CCL18 in the serum was linked with lymph node metastasis and worse histopathological typing, which was an independent influencing factor in the prognosis of patients with breast cancer." (PMID 31839826, 2019). "Here, we investigated whether CCL18, a chemokine produced by TAMs, can stimulate angiogenesis in breast cancer, as well as the underlying mechanisms." (PMID 26416449, 2015). "The role of CCL18 in cancer progression is controversial, it was reported that CCL18 could directly promote invasion, metastasis and angiogenesis in breast cancer, pancreatic cancer and ovarian cancer, but CCL18 was associated with prolonged survival in patients with gastric cancer." (PMID 36850011, 2023). "Thus, CCL18 released by TAMs correlated with increased breast cancer angiogenesis, which may cause poor clinical outcomes in patients with breast cancer." (PMID 26416449, 2015). "GPR77+ CAFs, driven by CCL18 signaling from TAMs, promote stemness and chemoresistance in breast cancer, but this effect can be reversed with anti-CCL18 therapy." (PMID 41441395, 2025). "TAMs, or myeloid derived monocytes (MDMs) activated with IL-4, promote breast cancer cell invasiveness, adherence to fibronectin and migration in vitro, through CCL18 secretion." (PMID 39044824, 2024). "CCL18 plays a role in promoting breast cancer, colon cancer, and squamous cell carcinoma metastasis, and CCR8 + Tregs are highly suppressive cells within the tumor." (PMID 38281962, 2024). "TAM-derived CCL18 induces EMT in breast cancer and activates ERK and Akt/GSK-3β/Snail signaling in human umbilical vein endothelial cells, thereby contributing to its pro-angiogenic effect." (PMID 39199574, 2024). "In breast cancer, a positive feedback loop was reported between mesenchymal-like cancer cells and macrophages via lactate and CCL18, promoting breast cancer metastasis." (PMID 38576043, 2024). "A previous study reported that naive CD4 + T cells were recruited and transformed into regulatory T cells (TREGs) by macrophage-derived CCL18 in breast cancer." (PMID 39816386, 2024). "Radiogenomic analysis identified 297 DEGs, including CXCL9, CCL18, and HLA-DPB1 which are known to be associated with breast cancer prognosis or angiogenesis." (PMID 38745321, 2024). "A recent study reported the upregulation of exosome derived miR-760 in breast cancer cells stimulated with TAM derived CCL18." (PMID 39044824, 2024). "CCL18 secreting TAMs were reported to be induced by breast cancer cell derived GM-CSF, with lactate —abundant in the TME—acting as a concomitant factor." (PMID 39044824, 2024). "CCL18 is reported to promote metastasis in breast cancer, colon cancer, and squamous cell carcinoma." (PMID 38281962, 2024). "In bi-MR, the causal association between CCL1 [OR (95%CI), 0.94 (0.89–0.99), p = 0.020] and CCL18 [OR (95%CI), 0.94 (0.89–1.00), p = 0.034] and breast cancer (finn-b-C3_BREAST) was found." (PMID 38075694, 2023). "The lower expression of CCL18 and TRGC1 was significantly correlated with favorable survival outcomes in breast cancer, while their higher expression was associated with poor prognosis." (PMID 36805828, 2023). "Consistently, compared with TGF-β-activated NBFs, CCL18-activated NBFs effectively reduced the chemotherapy-induced apoptosis of breast cancer cells." (PMID 36418470, 2023).
breast carcinoma (continued). "TAMs are induced by GM-CSF secreted by tumor cells, while TAM-secreted C-C motif chemokine ligand 18 (CCL18) induces EMT in breast cancer cells, thus forming a positive feedback loop to promote lung and liver metastasis." (PMID 37479694, 2023). "Meanwhile, it was found in breast cancer that M2 macrophages promote tumor angiogenesis by secreting CCL18." (PMID 36173487, 2023). "Cochrane’s Q test did not provide evidence of heterogeneity between CCL1 (p = 0.675) and CCL18 (p = 0.336) and breast cancer." (PMID 38075694, 2023). "Although the infiltration of CCL18+TAMs was much less in the chemosensitive cohort than chemoresistant cohort, the positive correlation between CD10+GPR77+ CAFs and CCL18+ TAMs was found across both chemoresistant and chemosensitive breast cancer cohorts." (PMID 36418470, 2023). "To further validate the cytokine array results, we performed immunohistochemistry staining for CCL18 in breast tumor biopsies from 259 breast cancer patients before neoadjuvant chemotherapy and correlated CCL18+ cell count with chemotherapeutic response." (PMID 36418470, 2023). "Breast cancer patients with CCL18 copy number variations, especially arm-level gains, showed significantly decreased immune cell infiltration." (PMID 36805828, 2023). "More importantly, the intratumoral injection of CCL18 into xenografts formed by MCF-7 cells co-implanted with NBFs dramatically reduced breast cancer cell apoptosis and sustained tumor growth in mice receiving chemotherapy." (PMID 36418470, 2023). "This then initiates a positive feedback loop between GM-CSF from breast cancer cells and CCL18 from TAMs that was shown in their humanized mouse model to drive tumor metastasis in vivo." (PMID 37370762, 2023). "As the key functional receptor for CCL18, PITPNM3 is expressed primarily on the cell surface of tumor cells and it has been reported that TAM secreted CCL18 interacted with its receptor PITPNM3 to promote breast cancer metastasis and angiogenesis." (PMID 36850011, 2023). "In colorectal cancer, osteosarcoma, head and neck squamous cell carcinoma, breast cancer, pancreatic ductal adenocarcinoma, lung cancer, etc., M2 macrophages all promote tumor invasion and metastasis by secreting CCL18." (PMID 36173487, 2023). "Let-7a is a downregulated miRNA in breast cancer that can inhibit the effects of CCL18 in BC cells by downregulating Lin28 expression." (PMID 35202089, 2022). "For example, CCL18 stimulation promoted the migration and invasion of breast cancer cells, which was induced by PCAF-dependent acetylation." (PMID 35609322, 2022). "Chemokine ligand 18 (CCL18), which is a breast cancer cell migration stimulatory factor, enhanced the activation of PyK2 in ovarian cancer cells (CaOV3 and OVCAR3)." (PMID 36555115, 2022). "Previously it was reported that GM-CSF promotes breast cancer pathogenesis by recruiting CCL-18+ macrophages into the tumor microenvironment." (PMID 36329016, 2022). "Tumor‐associated macrophages (TAMs)‐derived CCL18 activates the FAK or Pyk2/Src signaling to mediate the epithelial‐mesenchymal transition and invasion of breast cancer cells." (PMID 34459125, 2021). "TAMs are the main producers of CCL18, which was shown to promote breast cancer cell invasiveness and metastasis through stimulation of integrin clustering and by promoting adhesiveness to the extracellular matrix." (PMID 34503058, 2021). "M2 macrophages have been reported to enhance the invasion and metastasis of gallbladder cancer, breast cancer, and head and neck squamous cell carcinoma via the chemokine CCL18." (PMID 34922542, 2021). "Recent studies showed that ezrin and its interaction partner ACAP4 acetylation is involved in breast cancer metastasis in response to cytokine CCL18 stimulation." (PMID 32647287, 2020). "Recent study unraveled the importance of ezrin protein acetylation in CCL18-elicited breast cancer metastasis." (PMID 32647287, 2020).
breast carcinoma (continued). "Studies on patients’ material have shown that CCL18 expression is higher in tumor tissues than in normal ones in tumors such as cutaneous basal cell carcinoma, glioma, and breast cancer." (PMID 33114763, 2020). "CCL18 is also involved in the migration, invasion and metastasis of many neoplastic tumors, although it is its role in the metastasis of breast cancer that has been best studied." (PMID 33114763, 2020). "In 2011, NIR1 was validated to be a functional receptor of CCL18, and its dysregulation was noted to be involved in CCL18-induced calcium influx and chemotaxis in breast cancer." (PMID 32641093, 2020). "NIR1 is the most common receptor of CCL18, and their potent combination has been verified in breast cancer." (PMID 32641093, 2020). "The activation of NF-κB by CCL18 results in an increase in the expression of Lin28b in breast cancer cells." (PMID 33114763, 2020). "NIR1 can bind to CCL18, which further stimulates calcium signaling, and finally elicits a cancer-promoting function in various malignancies (e.g., breast cancer, non-small cell lung cancer and ovarian cancer)." (PMID 32641093, 2020). "In breast cancer, CCL18 produced by TAMs has been reported to promote cancer metastasis via PITPNM3-dependent calcium signaling activation." (PMID 33052231, 2020). "High expression of CCL18+ and SIGLEC1+ TAMs (markers identified by RNA-seq) in 456 breast cancer (USA) was significantly associated with shorter disease-specific survival (DSS)." (PMID 33194645, 2020). "Our findings demonstrate a novel role of IL-32θ as an intracellular modulator to suppress macrophage-promoted breast cancer progression by targeting CCL18-dependent signaling." (PMID 31126309, 2019). "RT-qPCR was used to analyze the mRNA expression of IL-32θ, Chemokine (C-C motif) ligand 18 (CCL18) in breast cancer tissues." (PMID 31126309, 2019). "In conclusion, IL-32θ inhibited EMT and metastasis in breast cancer cells by targeting CCL18 secreted from macrophages." (PMID 31126309, 2019). "GM-CSF secreted from breast cancer cells activates macrophages to become CCL18-expressing TAM-like cells, which reciprocally supports GM-CSF secretion and furthers EMT of breast cancer cells." (PMID 31126309, 2019). "Here, we provide evidence for a novel mechanism of Rho-GTPases regulating CCL-18-induced breast cancer migration." (PMID 31214501, 2019). "Experimental results demonstrate that the NP platform with larger size (NP-180) shows higher cellular uptake and efficient CCL-18 silencing in macrophages, leading to efficient inhibition of the breast cancer cell migration." (PMID 30618757, 2018). "It is known that CCL18 initiates Pyk2 and Src phosphorylation leading to breast cancer metastasis via its functional GPCR PITPNM3." (PMID 29738483, 2018). "A study showed that Pyk2 and Src play important roles during CCL18-induced breast cancer metastasis." (PMID 29738483, 2018). "CCL18 overexpression is observed in breast cancer, ovarian cancer, and glioma etc., which predicts a poor prognosis." (PMID 30181713, 2018). "We chose CC-chemokine ligand 18 (CCL-18) as a proof of concept therapeutic target and our results demonstrate that the CCL-18 silencing in macrophages can significantly inhibit the migration of breast cancer cells." (PMID 30618757, 2018). "It has also been shown that breast cancer metastasis can be mediated by CCL18 secretion in TAMs by activating PITPNM314." (PMID 30158589, 2018). "In another study, TAMs isolated from breast cancers were observed to secrete CCL18, which signals via the breast cancer cell-specific PITPNM3 receptor." (PMID 30356678, 2018). "Our results show that the optimal NP platform can efficiently silence the CCL-18 expression in macrophages, leading to significant inhibition of breast cancer cell migration." (PMID 30618757, 2018). "In vitro and in vivo experiments indicate that M2 TAMs-derived CCL18 promotes the metastasis in breast carcinoma and pancreatic ductal adenocarcinoma." (PMID 30181713, 2018).